ZKSCAN2 (zinc finger with KRAB and SCAN domains 2)
Description:
May be involved in transcriptional regulation.
Synonyms: ZNF694; FLJ23199; ZSCAN34
Tractability: PROTAC: UniProt records ubiquitination sites on it; ubiquitination databases record sites on it.
Target class: Transcription factor
Gene: Protein-coding gene on chromosome 16 (25,236,001 to 25,257,845, reverse strand). Ensembl gene ENSG00000155592.
Subcellular location: Nucleus
Subcellular location (Human Protein Atlas): Nucleoplasm; Golgi apparatus; Nucleoli fibrillar center
Gene Ontology:
Molecular function: DNA-binding transcription factor activity, RNA polymerase II-specific; RNA polymerase II cis-regulatory region sequence-specific DNA binding; DNA-binding transcription factor activity; sequence-specific double-stranded DNA binding
Biological process: regulation of transcription by RNA polymerase II; regulation of DNA-templated transcription
Cellular component: nucleus
Genetic constraint (gnomAD): Loss-of-function variants: 38 observed, 96.5 expected, observed/expected ratio (o/e) 0.39, 90% interval 0.3 to 0.52. The upper end of that interval is the gene's LOEUF score, 0.52, which puts it in group 2 of 6, group 1 being the genes least tolerant of losing a copy. Missense variants: 1,167 observed, 1,265.6 expected, observed/expected ratio (o/e) 0.92, 90% interval 0.88 to 0.97. Synonymous variants: 429 observed, 445 expected, observed/expected ratio (o/e) 0.96, 90% interval 0.89 to 1.04.
Homologues: Orthologues: chimpanzee ZKSCAN2 (99% identical), macaque ZKSCAN2 (95% identical), dog ZKSCAN2 (88% identical), pig ZKSCAN2 (87% identical), rabbit ZKSCAN2 (87% identical), mouse Zkscan2 (81% identical), rat Zkscan2 (81% identical), Drosophila melanogaster CG12391 (8% identical), Drosophila melanogaster hb (7% identical), zebrafish ovol1a (7% identical), zebrafish plagl2 (6% identical), zebrafish ovol1b (6% identical), and 4 more. Paralogues in human: ZSCAN29 (46% identical), ZSCAN32 (32% identical), ZNF18 (19% identical), ZNF496 (17% identical), ZNF274 (16% identical), ZNF202 (16% identical), ZNF174 (14% identical), ZSCAN5C (14% identical), ZNF446 (13% identical), ZSCAN5A (13% identical), ZSCAN5B (13% identical), ZSCAN18 (12% identical), and 17 more.
Diseases named in the same sentence as ZKSCAN2 in open-access papers:
ZKSCAN2 is named in the same sentence as 8 diseases in open-access papers, as found by Europe PMC text mining. Sharing a sentence is not in itself a finding about the gene and the disease.
ZKSCAN2 shares sentences with these, for which no sentence is quoted: breast carcinoma (1 paper); cancer (1); depression (1); insomnia (1); prostate carcinoma (1); psychiatric disorder (1); schizophrenia (1); tumor (1).